LEP (leptin)
Diseases named in the same sentence as LEP in open-access papers (continued):
Sharing a sentence is not in itself a finding about the gene and the disease.
Anxiety (continued). "Consistent with this, anorexigenic peptides such as leptin and cholecystokinin have been reported to increase anxiety-like behavior, whereas the orexigenic peptide neuropeptide Y (an established target for ghrelin in the arcuate nucleus) reduces anxiety-like behavior." (PMID 23071554, 2012). "However, some studies in non-pregnant women have reported that adiponectin, adipsin, leptin, and resistin may be associated with depressive and anxiety symptoms." (PMID 40565847, 2025). "In a study on Australianadolescents, the western diet pattern (i.e., high amounts of red meat, processedand refined foods, sweets, etc.)was found to be associated with higher BMI,waist circumference, depressive and anxiety symptoms, and CRP and leptin levels." (PMID 40110388, 2025). "The relationship between leptin, HPA axis activity, and anxiety in suicide attempters was reported recently." (PMID 36430254, 2022). "In fact, only mouse strains with higher levels of anxiety (e.g. DBA), when exposed to the ABA protocol, increased RWA showing the greatest decrease in the plasmatic levels of leptin." (PMID 34600568, 2021). "Some studies have demonstrated that chronic stress paradigms impair serum leptin levels, and the deletion of its receptor (long form) in hippocampus and VTA induces depressive- and anxiety-like behaviors." (PMID 30949073, 2019). "In a generalized linear model adjusting for relevant covariates, anxiety significantly interacted with LOC eating in relation to leptin (p = 0.02), such that greater trait anxiety related to higher concentrations of leptin only among youth with LOC eating." (PMID 31547319, 2019). "We found a significant correlation between leptin levels and the EPM anxiety index (r = 0.49, p = 0.032)." (PMID 27844058, 2016). "A leptin-triggered FEO reset would reduce energy-consuming foraging behavior, mediated either through changes in anxiety or through hippocampal control of the behavior itself, for a period during which such behavior would no longer be adaptive." (PMID 25814943, 2015). "As expected, acAN-TP1 patients had lower BMI-SDS and leptin concentrations and higher symptom levels (EDI-2, BDI-II, SCL-90-R anxiety scale) than HC, which improved after short-term weight restoration (except for anxiety)." (PMID 38461330, 2024). "Although our findings suggest that leptin may play a role in mediating somatic anxiety symptoms in MDD, the mechanisms of leptin-related somatic anxiety symptoms in MDD remain unclear." (PMID 35911226, 2022). "Subsequently, we found leptin predicted “somatic anxiety” symptoms in MDD, and leptin could be a significant and indirect mediator in the association between clinical status (MDD or FDR-MDD) and “somatic anxiety” symptoms." (PMID 35911226, 2022). "Our finding that leptin was a significant and indirect mediator of clinical status (MDD or FDR-MDD) and “somatic anxiety” symptoms suggests that leptin may indirectly affect somatic depressive symptoms in MDD." (PMID 35911226, 2022). "Bilateral ventral hippocampal leptin injections in mice affect spatial learning and memory without affecting anxiety-like behavior and locomotor activity in the elevated plus maze and open field." (PMID 34959795, 2021). "The most important neuropeptides that play a role in the modulation of stress-related behaviors and anxiety are cholecystokinin (CCK), oxytocin (OXT), substance P, neuropeptide Y, galanin, pituitary adenylate activator polypeptide (PACAP), ghrelin, and leptin." (PMID 32824625, 2020). "Regarding anxiety-like behavior evaluated in the open field test, leptin was not able to prevent LPS-induced anxiety-like behavior." (PMID 30949073, 2019). "Further prospective and mechanistic data are needed to clarify the nature of the relationship among leptin and LOC eating, and whether anxiety may drive this link." (PMID 31547319, 2019).
Anxiety (continued). "Trait anxiety was not significantly related to fasting serum leptin independently in a generalized linear model adjusting for age, race, height, sex, study type, and fat mass (kg)." (PMID 31547319, 2019). "In a large sample of youth of a broad age and weight range, the interaction between anxiety and LOC eating was significantly related to fasting serum leptin, such that only among youth with LOC eating, higher trait anxiety was related to higher concentrations of fasting serum leptin." (PMID 31547319, 2019). "Since attaining food triggers leptin release, this event could theoretically reset the FEO, both decreasing anxiety and hippocampal activity." (PMID 25814943, 2015). "Consumption of the HFD and downregulation of leptin in ob/ob mice did not significantly affect social behavior, as reflected by the SI ratio on the SI test and anxiety-like behaviors (based on the time spent in the central zone of the open-field test and arms of the elevated plus-maze test)." (PMID 35761401, 2022). "The relationship between depressive and anxiety symptoms of MDD and leptin remains unclear." (PMID 35911226, 2022). "However, anxiety, a prominent facet of psychosocial stress, has not been well-studied in relation to serum leptin among youth with LOC eating." (PMID 31547319, 2019). "Furthermore, by using the number of entries in the center of the open field as a parameter of anxiety-like behavior, we observed that LPS-induced anxiety-like behavior was not prevented by leptin administration." (PMID 30949073, 2019). "Thus, the negative correlations of leptin and concomitant depressive mood, anxiety, and stress found in LSS patients who had a mean BMI of 16.2 ± 0.9 kg/m2 before treatment are well in line with this study." (PMID 28030575, 2016). "Thus, leptin’s role in modulating anxiety-related behaviors at specific neural targets may be mediated, at least in part, by the upregulation of sympathetic nervous system (SNS) activity commonly observed in anxiety states." (PMID 40565847, 2025). "From the perspective of the mechanism of sugar on anxiety, on the one hand, sugar intake may participate in the neuroinflammatory process in brain regions by changing the levels of inflammatory factors such as IL-6, TNF-α, leptin, and iNO, leading to excessive production of nitric oxide." (PMID 39479195, 2024). "Despite the defects in insulin and leptin release during CORT treatment, Caps2 KO mice did not exhibit heightened anxiety/depressive behavior compared with WT mice." (PMID 25754523, 2015). "There may be other mechanisms that could explain the relationships among anxiety, LOC eating, and serum leptin that were not captured in the current analyses." (PMID 31547319, 2019). "Elevated levels of serum leptin can impair dopaminergic functioning and thus youth with LOC eating and elevated leptin may be driven to consume increased amounts of palatable foods in response to anxiety as a maladaptive attempt to cope with negative emotions." (PMID 31547319, 2019).
preeclampsia (102 papers, 2010 to 2025). Preeclampsia is a hypertensive disorder of pregnancy that is characterized by new-onset hypertension with proteinuria presenting after 20 weeks of gestation, and depending on mild or severe forms may initially present with severe headache, visual disturbances, and hyperreflexia. "Aberrant Expression of Metabolism-Associated Genes: canonical preeclampsia-associated genes—previously implicated in metabolic regulation, hypoxia, and angiogenesis—include LEP, HK2, FSTL3, FLT1, ENG, TMEM45A, ARHGEF4, and HTRA1." (PMID 41048968, 2025). "Systematic reviews also have confirmed that preeclampsia is linked to elevated levels of leptin and other adipokines throughout all pregnancy trimesters." (PMID 39544937, 2024). "In obese pregnant women, low serum concentrations of adiponectin and leptin in the first trimester have been associated with preeclampsia, indicating a potential role of adipokine dysregulation in its development." (PMID 39544937, 2024). "Increases in leptin levels preceding preeclampsia (by ~ 2 months) suggest that leptin can be used as a biomarker of the risk of preeclampsia." (PMID 37964253, 2023). "Several studies indicated a strong association between elevated placental leptin levels and preeclampsia (PE) pathogenesis and elevated serum interleukin-6 (IL-6) levels in PE patients." (PMID 38203306, 2023). "Logistic regression showed Bishop score (OR 1.5, p < 0.001), BMI (OR 0.92, P < 0.001), preeclampsia (OR 0.12, P = 0.010), use of multiple methods of induction (OR 0.22, P = 0.008) and leptin (OR 0.42, P = 0.017) were significantly associated with IOL outcome." (PMID 35031012, 2022). "The objective of this study was to investigate inflammatory markers such as adiponectin and leptin associated with preeclampsia." (PMID 36034841, 2022). "Further, leptin is involved in immune response and T-cell activation and has pro-inflammatory properties associated with adverse pregnancy outcomes, including preeclampsia, gestational diabetes, preterm birth, and intrauterine growth restriction." (PMID 34615489, 2021). "Two suggested dependencies either indicated leptin increase as a sign of placental stress, such as preeclampsia-associated hypoxia, or note its increase even before the onset of the disease, with the possibility of its use as a prognostic factor." (PMID 33321877, 2020). "Leptin, which has consistently been associated with preeclampsia in multiple large-scale proteomics studies can also activate the JAK/STAT5 pathway." (PMID 31263463, 2019). "Collectively, these correlations are consistent with earlier reports of associations of leptin with increased risks of preeclampsia and gestational diabetes." (PMID 24405869, 2014). "Instead, elevated serum leptin level and sFlt-1/PlGF ratio had an additive (joint) effect in the risk of preeclampsia, as shown by the substantially higher odds ratios of their combination than of either alone." (PMID 21906313, 2011). "It was shown that leptin causes lipid peroxidation in cultured human endothelial cells, therefore it has been suggested that leptin promotes atherogenesis in preeclampsia." (PMID 25587257, 2011). "Elevated leptin concentration in the first trimester of pregnancy appears to be associated with an increased risk of developing preeclampsia later in gestation." (PMID 21906313, 2011). "Furthermore, CCL-20 cord blood levels were associated with preeclampsia and fetal leptin, insulin, IL-8, and IL-10 levels, suggesting its role in pregnancy complications, fetal adiposity, and inflammation." (PMID 40698658, 2025). "In active women, decreases in leptin levels reduce the risk of preeclampsia by ~ 40%." (PMID 37964253, 2023). "Preeclampsia (PE) is associated with increased serum and placental leptin levels." (PMID 38203306, 2023). "Georgios Daskalakis reported that preeclampsia is associated with increased leptin (LEP)." (PMID 33335538, 2020).
preeclampsia (continued). "Many reports suggest that preeclampsia is associated with high serum and placental leptin levels." (PMID 32807109, 2020). "Furthermore, leptin is believed to have proinflammatory properties, and inflammation is associated with preeclampsia." (PMID 31737362, 2019). "These lists contain many candidates known to be involved in the pathophysiology of FGR, such as Flt-1 and LEP, which have been described in up to one third of the studies using placentas derived from pregnancies complicated by preeclampsia, a placental disorder frequently associated with FGR." (PMID 29983832, 2018). "Adverse physiological conditions during pregnancy such as maternal obesity and gestational diabetes have been associated with higher placental LEP methylation, whereas other studies have found lower placental LEP methylation in mothers with early-onset preeclampsia or impaired glucose metabolism." (PMID 27623604, 2017). "Furthermore, women with the LEPR 223A/G or 223G/G genotypes had an increased risk of developing severe preeclampsia compared with women with the 223A/A genotype, whereas 2548 G/A LEP polymorphism was associated with gestational diabetes mellitus." (PMID 28051281, 2016). "Leptin, a peptide hormone that regulates neuroendocrine function, also has inflammatory actions and has been implicated in adverse pregnancy outcomes, in particular preeclampsia." (PMID 26247200, 2015). "Elevated leptin concentrations (14.5 ng/mL) were associated with a 3.8-fold increased risk of preeclampsia (OR 3.8) whereas low soluble leptin receptor (SLR) (<28.5 ng/mL) was associated with a 6.3-fold increased risk of preeclampsia 6.3-fold (OR 6.3, 95%CI 1.7–23.2)." (PMID 24991435, 2014). "However, a clear picture of how an increased leptin is linked to the pathogenesis of preeclampsia remains to be elucidated." (PMID 22929622, 2012). "Moreover, the combination of elevated serum leptin level and sFlt-1/PlGF ratio was found to be additive for the risk of preeclampsia." (PMID 21906313, 2011). "Furthermore, elevated serum leptin level and sFlt-1/PlGF ratio had an additive (joint) effect in the risk of preeclampsia, as shown by the substantially higher odds ratios of their combination than of either alone." (PMID 21906313, 2011). "Furthermore, the combination of elevated serum leptin level and sFlt-1/PlGF ratio was found to be additive for the risk of preeclampsia." (PMID 21906313, 2011). "As described in paragraph 6.3, several adipokines, such as adiponectin, leptin, resistin, visfatin and apelin, are also secreted by the placenta and have been implicated in metabolic adaptations to normal gestation, as well as in preeclampsia and other complications of pregnancy." (PMID 31505789, 2019). "Deregulation of leptin metabolism and/or leptin function in the placenta may be implicated in the pathogenesis of various disorders during pregnancy, such as recurrent miscarriage, gestational diabetes, intrauterine growth restriction, and preeclampsia." (PMID 23056265, 2012). "In this study, the results demonstrated that healthy women have lower, statistically significant levels of adiponectin and leptin compared to women who have preeclampsia." (PMID 40990740, 2025). "Dysregulation of leptin expression is related to pathologies such as gestational diabetes, recurrent miscarriage, preeclampsia, and intrauterine fetal growth restriction Leptin production is enhanced by the cAMP, ERK, and PKA/PKC pathways." (PMID 40575259, 2025). "In conclusion, our study demonstrated that women with preeclampsia have higher levels of adiponectin and leptin biomarkers when compared to healthy women." (PMID 40990740, 2025). "Elevated early-pregnancy leptin levels are a recurrent observation in PE patients, and exogenous leptin administration in murine models recapitulates key clinical features of preeclampsia." (PMID 41048968, 2025).
preeclampsia (continued). "Regarding the comparison of leptin levels (ng/mL) among the preeclampsia and control groups, it was found that the serum levels of leptin were much higher in women with preeclampsia (p≤0.00001, I2=91%)." (PMID 40990740, 2025). "Previous studies also documented elevated placental biomarker 3-nitrotyrosine and hypomethylated leptin promoters in placental tissue on exposure to PM2.5 and black carbon, which has been linked to high-risk pregnancies such as preeclampsia." (PMID 38669277, 2024). "Experimental models have further demonstrated that leptin infusion can induce characteristics of clinical preeclampsia in mice, which can be mitigated by specific receptor deletions." (PMID 39544937, 2024). "Elevated leptin levels have been observed in some preeclampsia cases, suggesting its potential as a predictive marker." (PMID 39544937, 2024). "Several studies report that, in preeclampsia, some placenta-related markers, such as leptin, Inhibin-A, or sFlt-1, differ in concentration compared with uncomplicated pregnancies." (PMID 37237898, 2023). "The expression of LEP in the blood samples of patients with preeclampsia was significantly higher than that in control patients (p = 0.047); the expression of RAB6C was lower in the blood of patients with preeclampsia." (PMID 37389124, 2023). "We identified characteristic genes of preeclampsia as LEP, FLT1, RAB6C, and SASH1 using the GEO database and verified them using the GSE160888 and GSE96985 datasets." (PMID 37389124, 2023). "In the present study, the expression of LEP in the blood increased significantly in patients with preeclampsia and tended to increase in the placentas of patients with preeclampsia." (PMID 37389124, 2023). "Exercise can prevent gestational diabetes and preeclampsia by modulating levels of placentokines and exerkines, such as apelin, adiponectin, leptin, irisin, and chemerin." (PMID 37964253, 2023). "Cellular composition mediated a substantial proportion of the association between preeclampsia and FLT1 (37.8%, 95% CI [27.5%, 48.8%]), LEP (34.5%, 95% CI [26.0%, 44.9%]), and ENG (34.5%, 95% CI [25.0%, 45.3%]) overexpression." (PMID 36914823, 2023). "Characteristic genes, LEP, SASH1, RAB6C, and FLT1 can be used as diagnostic and therapeutic targets for preeclampsia, and they are associated with immune cell infiltration." (PMID 37389124, 2023). "Our findings suggest that LEP, SASH1, RAB6C, and FLT1 can be used as placental markers for preeclampsia and they are associated with various immune cells." (PMID 37389124, 2023). "The upregulation of miR-18b-3p inhibits the expression of LEP and reduces the occurrence of preeclampsia." (PMID 37389124, 2023). "The human placenta synthesizes and releases leptin, and increased serum leptin levels occur in rats and humans with preeclampsia." (PMID 37964253, 2023). "In the meta-analyses, we first evaluated leptin whose levels were significantly increased (p < 0.0002) in the group of women with preeclampsia compared to the control group." (PMID 36034841, 2022). "Some studies measuring leptin in the second and third trimesters of gestation found an increase in leptin levels in pregnant women with preeclampsia compared to the control group." (PMID 36034841, 2022). "Bishop score (OR 1.5, P < 0.001), BMI (OR 0.92, P < 0.001), preeclampsia (0.12, P = 0.01), use of multiple methods of induction (OR 0.22, P = 0.008) and leptin (OR 0.42, P = 0.02) were the only covariates significantly associated with successful IOL." (PMID 35031012, 2022). "Specifically, after controlling for BMI, Bishop Score, and preeclampsia, leptin was still predictive of a failed IOL with an odds ratio of 0.47 (P = 0.046)." (PMID 35031012, 2022). "For example, individuals suffering from mild and severe preeclampsia had higher levels of leptin compared to healthy pregnant women, where a positive correlation with the levels of the steroid hormone, estradiol was found." (PMID 35031012, 2022).